TET2 (tet methylcytosine dioxygenase 2)
Diseases named in the same sentence as TET2 in open-access papers (continued):
Sharing a sentence is not in itself a finding about the gene and the disease.
tumor (continued). "TET2 repression and 5hmC reduction is sufficient to enhance self-renewal capacity and tumor growth capacity of GSCs." (PMID 35136034, 2022). "S38-phosphorylated TET2 was found to be elevated in tumor tissues and negatively correlated with the tumor pathological grade." (PMID 35223782, 2022). "In the present study, qRT-PCR data from 15 paired FPH ccRCC samples revealed that while NOP2 and NSUN6 were upregulated, TET2 was downregulated in tumor tissues compared with those in normal tissues." (PMID 35309925, 2022). "Compared with the adjacent mucosa, the expression of NSUN3 (p < 0.001) and TET2 (p < 0.001) in the tumor group was significantly downregulated." (PMID 35281843, 2022). "A similar pattern is observed at the tumor suppressor and Super-enhancer Domain gene Tet2, whose expression is decreased by 65% in SMC1A-R586W mESCs." (PMID 33760811, 2021). "TET2/DNMT3A mutation status in 47,571 human tumor samples was analyzed at cBioPortal for Cancer Genomics." (PMID 34039392, 2021). "Clinical data from specific DLBCL tumour samples presented interesting characteristics and relationships when both TET2 and miR-92a expression were considered." (PMID 34899857, 2021). "The results from functional experiments suggested that the tumor-suppressive role of GATA6-AS1 in OC was partly dependent on its regulatory function on TET2." (PMID 34429758, 2021). "Another study has shown that TET1 and TET2 enzymes have distinct functions in T-ALL development; TET1 acts as an oncogene in T-ALL, while TET2 is tumor suppressing." (PMID 33573325, 2021). "Here, our findings suggest that DNA-demethylating agents can rescue aberrant silencing of the key tumor suppressor, TET2 in T-ALL cells." (PMID 34413196, 2021). "Compared with the control group, the weight of tumor in TET2 KO group was much heavier while the TET2 ACT group showed opposite result (P< 0.01)." (PMID 34019487, 2021). "Genetic studies into TET2 have revealed the link between alterations in DNA methylation and tumour metabolism." (PMID 34065087, 2021). "Among genes with reduced enhancer-promoter loops were known tumor suppressors such as Tet2, Dusp4, as well as MHC class II genes." (PMID 34621263, 2021). "A study using a mouse model with combined mutation of TET2, FLT3-ITD, and IDH2-R140Q; thus, triple-transformed leukemia, showed tumor sensitivity both to 5-azacytidine and to IDH2 inhibitor enasidenib." (PMID 34947882, 2021). "In lymphoid lineage malignancy, however, TET1 appears to play a tumor suppressor role comparable to TET2." (PMID 36618446, 2021). "Together, our results reveal TET2 as a potential tumor suppressor in T-ALL and a marker for response to 5-aza in this poorly understood malignancy." (PMID 34413196, 2021). "The reduction of Tet2 enhancer promoter loop strength observed in this global analysis prompted us to look more closely at this tumor suppressor gene." (PMID 34621263, 2021). "A correlation between increased tumor risk or severity with the mutated DNA‐modifying enzymes DNMT3A and TET2 has been observed." (PMID 34754417, 2021). "The expression of miR-92a-3p and miR-92a-5p mature miRNAs and TET2 mRNA were assayed in NHL patient tumour biopsies and compared to healthy control PBMCs by RT-qPCR." (PMID 34899857, 2021). "Increased glucose levels hinder AMPK-mediated human TET2 phosphorylation at serine 99, resulting in the destabilization of TET2 followed by dysregulation of both 5hmC level and the tumor suppressive effect of TET2 in vitro and in vivo." (PMID 33085059, 2021). "In melanoma and colon tumor cells deletion of Tet2 reduced chemokine expression and tumor-infiltrating lymphocytes, enabling tumors to evade antitumor immunity and to resist anti-PD-L1 therapy." (PMID 34417463, 2021).
tumor (continued). "Furthermore, RNA-seq analysis showed that TAMs from Mye-Tet2 null mice overexpressed genes associated with the M1 pro-inflammatory signature, while typical genes of M2 immunosuppressive macrophages, among which Arg-1, were down-modulated, compared to TAMs from wild-type tumor-bearing mice." (PMID 33212945, 2020). "The TET2 gene is considered a tumour suppressor gene that can regulate gene transcription by catalysing DNA demethylation, thus regulating haematopoietic function." (PMID 33160401, 2020). "Downregulation of TET2 promotes gastric cancer cisplatin resistance via regulating interleukin-6 expression in the tumor microenvironment." (PMID 32774157, 2020). "Alternatively, AMPK phosphorylates and stabilizes another epigenetic master regulator, Tet methylcytosine dioxygenase 2 (TET2), which functions as a putative tumor suppressor to prevent tumorigenesis." (PMID 32807225, 2020). "Accordingly, TET2 played a tumor suppressor role to promote apoptosis and restrain proliferation, migration, and invasion of BC cells." (PMID 33146288, 2020). "Based on the expression of these 5mC regulators, we investigated the mRNA expression levels of regulators between the normal and tumor groups and found that most of the regulators (except TET2) were significantly expressed in the tumor group." (PMID 33195409, 2020). "Clinicopathological features analyses showed that decreased IHC signal of TET2 was correlated with larger tumor size (P = 0.036)." (PMID 33097695, 2020). "Tet2-KO mice recapitulate characteristics of patients with myeloid cancer, indicating that Tet2 plays a functional role as a tumor suppressor to sustain hematopoietic cell homeostasis." (PMID 33184433, 2020). "In our cases, positive expression of TET2 was detected in 20 (25.6%) of the tumor tissues, while only 50 (43.1%) of the adjacent normal specimens showed a positive signal (P = 0.009)." (PMID 33097695, 2020). "For example, increased expression of TET2 promotes melanoma progression by suppressing tumor-infiltrating myeloid cells." (PMID 32774157, 2020). "All of these interactors, and other small-molecule activators of Tet2, would be helpful methods for stabilizing in vitro-generated immune cells or modified tumor cells for potential clinical utilization." (PMID 33184433, 2020). "Mice with myeloid cell-specific Tet2 deletion exhibit diminished tumor growth, and enhanced tumor-infiltrating T cells; moreover, T-cell depletion suppresses the attenuated tumor progression." (PMID 33184433, 2020). "Apart from RHOA and TET2 mutations, a high frequency of diverse mutations in TCR signaling-related genes were also present in AITL tumor samples (11/12, 91.7%)." (PMID 30814910, 2019). "This study provides novel evidence that MYC directly deregulates the expression of TET1 and TET2 in T-ALL to maintain 5mC and 5hmC patterns in a genome-wide fashion, which is associated with tumor cell-specific gene expression." (PMID 31266538, 2019). "While the exact role of TET1 and TET2 in regulating DNA (hydroxy)methylation outside of developmental processes is not well understood, our findings indicate distinct functions of TET1 and TET2 in MYC-driven tumor maintenance." (PMID 31266538, 2019). "We conclude that ectopic TET2 expression in human T-ALL disrupts tumor cell growth and results in reduced cell proliferation primarily through necrosis." (PMID 31266538, 2019). "Here, we report that in T-ALL, the MYC oncogene controls the expression of both TET1 and TET2, which in turn contribute to tumor cell-specific 5mC and 5hmC patterns in a genome-wide fashion with importance for tumor maintenance." (PMID 31266538, 2019). "Significantly, they demonstrated that TET2 is involved in glucose-modulated tumor growth, and AMPK activator metformin suppressed tumor growth partly by altering global 5hmC, through phosphorylating TET2 by AMPK." (PMID 31164154, 2019).
tumor (continued). "Tet methylcytosine dioxygenase 2 (TET2) is a tumor suppressor gene that is inactivated in a wide range of hematological cancers." (PMID 31231651, 2019). "Hyperglycemia inhibited phosphorylation of TET2 (a tumor suppressor), resulting in its destabilization, and dysregulation of its tumor suppressive activity and its substrate, 5-hydroxymethylcytosine (5hmC), in vitro as well as in vivo." (PMID 31546918, 2019). "Genetic inactivation of tet2 results in macrophage-dependent recruitment of effector T-cells and anti-tumor activity, suggesting that tet2 has a tumor-promoting effect." (PMID 31557902, 2019). "Our data indicated that STAT5 and TET2 were significantly upregulated in tumor-infiltrating CD4+ T cells of CRC." (PMID 30013992, 2018). "TET2 dysregulation is also present in other tumor types, in some of which TET2 downregulation has been found to be associated with poor prognosis and reduced patient survival." (PMID 29899831, 2018). "In conclusion, we demonstrated that the excessive expression of FOXP3 in tumor-infiltrating CD4+ T cells of CRC patients is caused, at least in part, by the upregulation of STAT5 and TET2." (PMID 30013992, 2018). "Aberrant 5 hmC patterns are common in certain tumor types, and TET2 has been described as a tumor suppressor gene in many cancers." (PMID 29899831, 2018). "The results from real-time PCR showed that STAT5 and TET2 expression was significantly upregulated in tumor tissues compared with normal tissues." (PMID 30013992, 2018). "In patient P1, the contribution of germline DNA in the tumor sample was less than 10% since the 2 bp deletion of TET2 has a VAF of 90%, which suggest a tumor purity of about 90%." (PMID 30213991, 2018). "Upregulation of TET2 in the KDM2A-depleted cells induces the re-activation of two TET downstream tumor suppressor genes, epithelial cell adhesion molecule (EpCAM) and E-cadherin, and inhibits migration and invasion." (PMID 28785073, 2017). "In some tumor models, TET2 expression has been shown to be repressed via hypermethylation of CpG islands located in its genomic sequence." (PMID 28881727, 2017). "The increased TET2 expression in these cells exerts a tumor-promoting effect, since it sustains the immunosuppressive activity of these cells." (PMID 29156643, 2017). "We then established xenograft models via subcutaneous injection of 5×106 cells into the flanks of C57BL/6 mice to test the effects of TET2 expression on tumor growth and survival of the mice." (PMID 27852070, 2017). "The significance of 5-hmC loss specifically in cancer cells became further evident when reintroduction of the 5-hmC by recombinant IDH2 or TET2, suppressed tumor growth and increased tumor-free survival in the melanoma mouse models." (PMID 29290954, 2017). "The overexpression of the TET2 C-terminal sequence significantly delayed the appearance of macroscopic tumors and decreased the tumor weights by 35 days after injection." (PMID 27852070, 2017). "We provide direct evidence that ATLL tumor cells display low global 5-hmc level as compared to normal T cells and that levels of 5-hmc and TET2 further distinguish tumor T cells from acute patients from those of chronic patients." (PMID 28881727, 2017). "Numerous loss-of-function mutations of tet2 have been identified in myeloid cancers where tet2 has been shown to be a key tumor suppressor." (PMID 29100458, 2017). "Methylation of DNA is an important force to promote tumor formation and malignant progression, 5hmC is in the TET2 enzyme catalyzed by 5mC oxidation, 5hmC is a metabolic product of 5mC, which will lead to a decline in 5mC, and demethylation." (PMID 29029424, 2017). "While the difference was less pronounced than for 5-hmc, lower TET2 staining was found as well in tumor T cells as compared to normal T cells, suggesting that TET2 accounts, at least in part, for the variation in 5-hmc found between these two populations." (PMID 28881727, 2017).
tumor (continued). "RHOA mutations were identified only in PD1+ cells in 100% cases, while TET2 and DNMT3A mutations were identified in both the PD1+ cells and CD20+, tumor-cell-depleted cells in the majority of cases." (PMID 28157189, 2017). "To confirm that mutations associated with the tumours in aged Tet2−/− mice were somatic, we performed additional WES using Lin−c-Kit+ (LK) cells isolated from premalignant (6-week-old) WT, Tet2+/− and Tet2−/− mice." (PMID 28440315, 2017). "The impact of harboring the rs72963007 TET2 allele or a TET2 somatic mutation on genomic hydroxymethylation and TET2 expression in ATLL tumor T cells was next studied." (PMID 28881727, 2017). "Tet methylcytosine dioxygenase 2 (TET2) is a putative tumor suppressor gene located on chromosome 4q24.1." (PMID 28407691, 2017). "It is well established that an aberrant hypermethylation of tumor DNA can be caused by mutations in epigenetic modifiers such as IDH1, IDH2, TET1, TET2, and SDH-subunits." (PMID 26848979, 2016). "So, the correlation of the 5-hmC level and TET2 expression in ESCC tumor tissues need to be further studied in a larger samples or using other method to detect the 5-hmC level." (PMID 27050164, 2016). "In our study, we have only found the significant correlation between the down-regulation of TET2 and decreased 5-hmC when compared tumor tissues with normal tissues." (PMID 27050164, 2016). "The gene TET2 located in the locus 4q24 increased in copy number with higher frequency in the transition to central tumour and lower frequencies in the transition to lymph node and bony metastases." (PMID 27653089, 2016). "Compared with non-tumor tissues, TET2 and TET3 were significantly downregulated in ESCC tissues (P < 0.01), whereas TET1 expression showed no significant decrease in ESCC tissues." (PMID 27050164, 2016). "Restoration of the 5-hmC landscape via TET overexpression has been shown to inhibit melanomagenesis in experimental xenograft models, suggesting a potential tumor suppressive role of TET2 function and 5-hmC." (PMID 26462027, 2015). "Recently, it was reported that reintroduction and overexpression of TET2 in human melanoma cells restores 5hmC content and suppresses tumor invasion and growth." (PMID 24152442, 2013). "All of these results suggested crucial roles of TET2 nuclear increase during tumor progression." (PMID 41605908, 2026). "Because TET2 inhibition impairs PD-L1 transcription and confers tumor resistance to immunotherapy 29, we investigated whether augmenting TET activity through CPS1 inhibition enhances programmed death-ligand 1 (PD-L1) expression." (PMID 41356199, 2026). "When TET2 mutation is detected in nonhematological tumor samples, clonal hematopoiesis can be difficult to differentiate from tumor‐specific somatic mutations." (PMID 40116537, 2025). "In myeloid malignancies, TET2 acts as a key tumor suppressor." (PMID 40599235, 2025). "The genetic alterations in 12 PDX specimens suggest persistence of TET2 and DNMT3A loss during tumor passaging, but RHOAG17V showed more variations with disappearance in some PDX models and re‐emergence that follows TET2 loss in some after several passages, indicating more dynamic clonal selection." (PMID 40510016, 2025). "In addition, this study found that the anticancer drug 5‐azacytidine (5‐AZA) prevents HCC tumor cell growth by inducing the expression of TET2 and TET3." (PMID 40599235, 2025). "Moreover, the increased sequencing depth and tumor enrichment identified additional variants, and mutations in TET2 and/or IDH2R172K were detected in three cases that were previously unable to be detected in the whole tumor sample." (PMID 40510016, 2025). "The correlation was driven by Tet2-mutant tumor-infiltrating myeloid cells, including mononuclear phagocytes (monocytes, macrophages and dendritic cells) and granulocytes (neutrophils and eosinophils), although the former were affected more profoundly by blood CHIP levels." (PMID 40267425, 2025).
tumor (continued). "Compared with the siNC-MDSCs group, the tumor size of the siTET2-MDSCs group was reduced, and the tumor volume was decreased in the siTET2-MDSCs group, suggesting that interfering with the expression of TET2 in MDSCs could delay tumor growth." (PMID 40917754, 2025). "In the absence of drug intervention, TET2 deficiency significantly enhances tumor cell viability in HCC cell lines." (PMID 40473594, 2025). "In other cases, however, TET2, DNMT3A, and TET3 variants, appeared to be tumor specific." (PMID 40510016, 2025). "By comparing the VAFs of mutations between tumors and paired bone marrow samples without obvious tumor infiltration in eight TET2 mutation cases, three patterns of TET2 mutation configuration were observed, consistent with the previous study." (PMID 40164718, 2025). "Interestingly, TET2 deletion promotes the expansion of TFH tumor cells through the CD40–CD40LG axis, leading to the development of AITL." (PMID 40599235, 2025). "Inhibiting TET1 or activating TET2 was found to reverse tumor progression." (PMID 40520993, 2025). "However, aberrant TET2 expression is frequently observed in certain tumor cells and cells infected by viruses." (PMID 39840982, 2025). "Likewise, TET2 knockdown decreases E‐cadherin and EpCAM levels and is correlated with increased tumor invasiveness." (PMID 40116537, 2025). "Deep sequencing revealed skewed predominance of a single T cell clone, representing >90% of CAR T cells, which was not detectable in the pre-infusion product and was subsequently found to harbour a SIN-LV insertion into the methylcytosine dioxygenase TET2 gene site, a known tumour suppressor gene." (PMID 40200078, 2025). "In this study, we investigated whether TET2 plays a role in demethylating the tumor suppressors and activation of their expression." (PMID 39057134, 2024). "Furthermore, HCC patients with high tumor TET2, p-STAT5A, cGAS, LRRC8C, and endothelial STING expression had better clinical outcome." (PMID 38177099, 2024). "Therefore, cancer cells are the dominant source of cGAMP in the tumor microenvironment, especially when their cGAS expressions are upregulated by TET2 in this study." (PMID 38177099, 2024). "Moreover, the significantly positive correlations among the expression levels of TET2 in para-tumor tissues were generally attenuated or even disappeared in LIHC tumor tissues." (PMID 39104395, 2024). "Proliferation of the TET2-KO clones was similar to the WT clone, indicating that loss of TET2 expression in CT-26 tumor cells does not affect tumor cell proliferation or survival." (PMID 39388288, 2024). "Increased antigen presentation pathway gene expression is TET2 dependent in tumor cells." (PMID 39388288, 2024). "For example, TET2 acted as a tumor suppressor in solid tumors and could predict patient response and the efficacy of anti-PD-1/PD-L1 therapy." (PMID 38317133, 2024). "Moreover, significantly weaker expressions of TET2 were found in tumor tissues than in normal/marginal prostate (p = 0.0028) and BPH tissues (p = 0.0004)." (PMID 39471555, 2024). "TET2+5hmC+ (high TET2 and high 5hmC) association was significantly associated with well differentiation, myometrial invasion, negative lymph node metastasis, and tumor stage in EC." (PMID 38515066, 2024). "To test whether VC also induces antigen presentation in tumor tissue, we isolated cells from WT or TET2-KO B16-OVA syngeneic tumor tissue treated with VC or PBS." (PMID 39388288, 2024). "Accordingly, stimulating tumor TET2 by VC to accelerate this positive feedback loop may effectively induce tumor vascular normalization and boost immunotherapy efficacy." (PMID 38177099, 2024). "We performed molecular function pathway analysis for tumor clusters C0 and C2 and found major mechanisms associated with antigen presentation functions (such as MHC protein complex binding and MHC class II complex binding) enhanced by VC treatment, which was lost in the TET2-KO tumor clusters." (PMID 39388288, 2024).